NFATC2IP (nuclear factor of activated T cells 2 interacting protein)
Description:
In T-helper 2 (Th2) cells, regulates the magnitude of NFAT-driven transcription of a specific subset of cytokine genes, including IL3, IL4, IL5 and IL13, but not IL2. Recruits PRMT1 to the IL4 promoter; this leads to enhancement of histone H4 'Arg-3'-methylation and facilitates subsequent histone acetylation at the IL4 locus, thus promotes robust cytokine expression (By similarity). Down-regulates formation of poly-SUMO chains by UBE2I/UBC9 (By similarity).
Synonyms: NIP45; FLJ14639; RAD60; ESC2
Tractability: PROTAC: UniProt records ubiquitination sites on it; ubiquitination databases record sites on it; its protein half-life has been measured.
Gene: Protein-coding gene on chromosome 16 (28,950,807 to 28,967,092, forward strand). Ensembl gene ENSG00000176953.
Subcellular location: Nucleus; Cytoplasm
Subcellular location (Human Protein Atlas): Nucleoplasm
Gene Ontology:
Biological process: positive regulation of transcription by RNA polymerase II; protein sumoylation
Cellular component: cytoplasm; nucleus
Genetic constraint (gnomAD): Loss-of-function variants: 23 observed, 33 expected, observed/expected ratio (o/e) 0.7, 90% interval 0.5 to 0.99. The upper end of that interval is the gene's LOEUF score, 0.99, which puts it in group 4 of 6, group 1 being the genes least tolerant of losing a copy. Missense variants: 528 observed, 507.49 expected, observed/expected ratio (o/e) 1.04, 90% interval 0.97 to 1.12. Synonymous variants: 234 observed, 212.83 expected, observed/expected ratio (o/e) 1.1, 90% interval 0.99 to 1.23.
Homologues: Orthologues: chimpanzee NFATC2IP (98% identical), macaque NFATC2IP (89% identical), dog NFATC2IP (77% identical), pig NFATC2IP (77% identical), rabbit NFATC2IP (74% identical), rat Nfatc2ip (70% identical), mouse Nfatc2ip (69% identical), tropical clawed frog nfatc2ip (32% identical), zebrafish nfatc2ip (24% identical). Paralogues in human: SUMO2 (7% identical), SUMO3 (7% identical), SUMO4 (7% identical).
Diseases named in the same sentence as NFATC2IP in open-access papers:
NFATC2IP is named in the same sentence as 16 diseases in open-access papers, as found by Europe PMC text mining. Sharing a sentence is not in itself a finding about the gene and the disease. The quoted sentences say what the papers report.
cardiac hypertrophy (2 papers, 2024 to 2025). "The study points to a new pathogenic mechanism for microRNA‐associated cardiac hypertrophy, suggesting the miR‐31‐5p/Nfatc2ip/β‐Mhc pathway as a potential target for cardiac hypertrophy." (PMID 38894694, 2024). "Taken together, our findings showed that miR‐31‐5p was downregulated in AAC‐induced rats, leading to the suppression of Nfatc2ip removed, resulting in upregulated b‐Mhc, which initiates cardiomyocyte remodelling in the early stage of cardiac hypertrophy." (PMID 38894694, 2024). "Further, we found that Nfatc2ip activates β‐Mhc transcription by targeting the core‐promoter of β‐Mhc, and miR‐31‐5p inhibits Nfatc2ip‐β‐Mhc signalling to prevent cardiac hypertrophy." (PMID 38894694, 2024). "Above all, our study found a new pathway, mir‐31‐5p/Nfatc2ip/β‐Mhc, which is involved in cardiac hypertrophy, suggesting a potential target for intervention of cardiac hypertrophy." (PMID 38894694, 2024). "Mechanistically, miR‐31‐5p suppresses cardiac hypertrophy in vivo and in vitro by targeting Nfatc2ip." (PMID 38894694, 2024). "Conducted on animal models (rats with abdominal aortic coarctation), the study indicates that this microRNA modulates the expression of the Nfatc2ip gene, a transcription factor involved in the activation of the β-Mhc gene, which is essential in cardiac hypertrophy." (PMID 40725061, 2025). "Moreover, we first found out that Nfatc2ip is upregulated in the early stage of myocardial hypertrophy, and the overexpression of Nfatc2ip‐induced myocardial hypertrophy is rescued by si‐Nfatc2ip RNA." (PMID 38894694, 2024). "Furthermore, we verified that Nfatc2ip is necessary and sufficient for cardiac hypertrophy in neonatal rat cardiomyocytes." (PMID 38894694, 2024). "miR‐31‐5p targets the 3′UTR of Nfatc2ip and inhibits myocardial hypertrophy in vitro and in vivo." (PMID 38894694, 2024). "To explore the mechanism of miR‐31‐5p suppressing cardiac hypertrophy, we analysed its potential targets using bioinformatic programmes, including miRbase, microRNA.org and miRcode, predicting that miR‐31‐5p may effectively target Nfatc2ip through binding its 3′‐UTR." (PMID 38894694, 2024). "Nfatc2ip is one of the NFAT families, which has been thought to promote cardiac hypertrophy and pathological remodelling, and disrupt NFAT signalling to attenuate cardiac hypertrophy." (PMID 38894694, 2024).
Burkitt lymphoma (1 paper, 2006). A rare form of malignant mature B-cell non-Hodgkin lymphoma. "The NF-ATc2 isoform has been found to participate in the BCR-induced apoptosis in B-cell-derived Burkitt's lymphoma cell lines, thus the presence of Nfatc2ip and Fkbp1 suggests that these interacting proteins may also be important in regulating Ca++/calmodulin/calcineurin/NFAT signaling in B cells." (PMID 16670020, 2006).
type 2 diabetes (1 paper, 2026). "Notably, one CpG connected to NFATC2IP (Nuclear Factor of Activated T-cells 2 Interacting Protein) plausibly influences both IL-6 production and multiple immunometabolic conditions, including body mass index and type 2 diabetes." (PMID 41639309, 2026).
infection (1 paper, 2013). The state of being infected such as from the introduction of a foreign agent such as serum, vaccine, antigenic substance or organism. "By contrast, the pool of genes induced during ΔF2 Nig06 infection is mainly involved in the mounting of an immune response: Trem1, Kng1, Nfatc2ip and Xcr1 are particularly implicated in mediation of inflammation, cytokine induction and leukocyte chemoattraction." (PMID 23469251, 2013).
NFATC2IP also shares sentences with these, for which no sentence is quoted: allergic asthma (2 papers); allergies (2); asthma (2); cancer (2); tumor (2); airway hyperresponsiveness (1); atopic eczema (1); breast carcinoma (1); diabetes (1); eosinophilia (1); Obesity (1); osteosarcoma (1).